DTL (denticleless E3 ubiquitin protein ligase adapter)
Diseases named in the same sentence as DTL in open-access papers (continued):
Sharing a sentence is not in itself a finding about the gene and the disease.
cancer (55 papers, 2009 to 2026). A tumor composed of atypical neoplastic, often pleomorphic cells that invade other tissues. "DTL overexpression has been reported to be associated with poor patient survival in many types of cancer." (PMID 40723362, 2025). "Of the identified hub genes, DTL—an E3 ubiquitin ligase linked to the CRL4 complex—plays a central role in cancer progression, impacting tumor growth, invasion, and metastasis, as well as cell cycle regulation and epithelial-mesenchymal transition (EMT)." (PMID 39567714, 2024). "It is reported DTL depletion in cancer cells caused apoptotic death of cancer cells associated with rereplication due to the loss of CDT1 degradation, but not in non-transformed cells." (PMID 31409387, 2019). "Depletion of DTL caused rereplication and appearance of multipolar spindles, spindle formation characteristics of cancer cells." (PMID 25186767, 2014). "To identify whether DTL gene mutations are related to cancer, we downloaded the processed mutation data from 33 types of tumors from TCGA to analyze the mutations in these tumors." (PMID 37038185, 2023). "Notably, previous studies have shown that DTL expression is elevated in many cancers, and the abnormal expression of DTL is also associated with poor prognosis." (PMID 34712733, 2021). "Moreover, silencing PDCD4 rescued cancer cell growth and mobility deficiencies caused by DTL knockdown." (PMID 31409387, 2019). "It was also verified that overexpression of DTL could regulate the cell cycle, promote cell proliferation and cause genomic instability in cultured cells, which may be the reason why DTL plays a role in the occurrence, progression and treatment of cancer." (PMID 37038185, 2023). "Other studies have illuminated that DTL was involved in the tumorigenesis as well as in the proliferation, migration, and invasion of cancer cells." (PMID 40391156, 2025). "Elevated DTL expression correlates with poor prognosis, tumor aggressiveness, and metabolic alterations that enhance cancer cell proliferation and migration, highlighting its key role in promoting BC development." (PMID 40391156, 2025). "Another significant gene, DTL, part of the ubiquitin-proteasome system involving CUL4A, shows elevated expression in cancers, and DTL knockdown hinders cancer cell functions." (PMID 39567714, 2024). "This comprehensive inquiry aimed to unravel the intricate expression patterns of CDK1 and DTL across these diverse cancer studies." (PMID 39567714, 2024). "As previously reports, overexpression of DTL has been found in many cancers and correlated with poor prognosis of cancer patients." (PMID 37038185, 2023). "DTL, an E3 ubiquitin-protein ligase, has also been shown a poor prognostic role to promote cancer progression in several cancer types." (PMID 36849756, 2023). "Previous studies have shown that DTL was involved in the tumorigenesis and the proliferation, migration and invasion of cancer cells." (PMID 37038185, 2023). "Overexpression of DTL in LIHC was also verified by IF and obvious cancer nests had stronger expression of DTL than surrounding tissues." (PMID 37038185, 2023). "DTL overexpression has been found in many types of cancers and shown to correlate with poor patient outcome in certain tumors." (PMID 37038185, 2023). "DTL was previously found to play a crucial role in cancer development by degrading the programmed cell death 4 protein, leading to cancer progression." (PMID 37689310, 2023). "DTL is a master coordinator of cell cycle progression and is involved in carcinogenesis and development of various cancers." (PMID 38133379, 2023).
cancer (continued). "The mRNA levels of DTL were significantly elevated in liver tumor tissues than in adjacent normal tissues and, interestingly, demonstrated a pan-cancer upregulation characteristic, implying the crucial role of DTL in tumorigenesis and progression." (PMID 35392073, 2022). "Meanwhile, two candidate genes (ADRA2A and DTL) obtained by comparison screening have been reported in cancer." (PMID 34490040, 2021). "Denticleless E3 ubiquitin protein ligase homolog (DTL) gene with oncogenic function has been evaluated in several cancers." (PMID 34635635, 2021). "Above all, DTL was overexpressed in cancer tissues and related to the poor outcomes of cancer patients." (PMID 31409387, 2019). "Above all, our data provided novel mechanistic insights into the function of DTL in cancer progression." (PMID 31409387, 2019). "In turn, silencing DTL slowed down the cancer cell growth rates and weakened the colony formation abilities of cancer cells." (PMID 31409387, 2019). "Denticleless E3 ubiquitin protein ligase homolog (DTL) has been identified in amplified region (1q32) of several cancers and has an oncogenic function." (PMID 26472028, 2015). "In conclusion, a novel molecular signature panel including the AURKA, CEP55, DTL, and TTK genes could improve early cancer detection and diagnostic accuracy, and it may contribute to the treatment outcomes of PAN-gastrointestinal cancer patients." (PMID 40723362, 2025). "In addition, we also found that DTL expression is significantly positively correlated with the expression of most ICP genes in many cancers." (PMID 37038185, 2023). "The overexpression of DTL was correlated with poor prognosis in most cancers." (PMID 37038185, 2023). "In high-risk human papillomavirus (HPV)-induced cancer, USP46 recruited by oncoprotein E6 leads to deubiquitination and stabilization of Cdt2/DTL, a component of the E3 ligase CRL4Cdt2, and represses the level of epigenetic regulator Set8, which promotes cell proliferation." (PMID 35283827, 2022). "DTL (Denticleless E3 ubiquitin protein ligase homolog) and SKP2 (S-phase kinase-associated protein 2) could degrade cancer progression via PDCD4 ubiquitination." (PMID 33996533, 2021). "Overexpression of DTL accelerated tumor cell growth and increased invasive ability of cancer cells." (PMID 31409387, 2019). "DTL, one of the CUL4-DDB1 associated factors (DCAFs), may involve in the process of cancer development." (PMID 31409387, 2019). "Remarkably, previous studies showed that DTL expression was elevated in many cancers." (PMID 31409387, 2019). "Expression of the DTL protein was observed in both the cytoplasm and nucleus of cancer cells." (PMID 26472028, 2015). "In addition, overexpression of DTL in cancer was confirmed in liver, bladder and stomach samples." (PMID 37038185, 2023). "Thus, given the significance of immunotherapy in the management of malignant tumors, targeting DTL might provide us with fresh perspectives on OS therapy." (PMID 37439040, 2023). "In our pan-cancer analysis, we observed that the expression of the CRL family member DTL was upregulated in multiple tumor tissues, with a particularly pronounced increase in BC." (PMID 40391156, 2025). "For example, even if DTL is almost undetectable in normal human tissues, it is the most essential DCAF with a BF over 100 in cancer cell lines." (PMID 37689310, 2023). "Overexpression of DTL was significantly related to the prognosis, immune infiltration, ICP, and immunotherapy across cancers." (PMID 37038185, 2023). "The results of IHC staining confirmed that the expression of DTL in LIHC was significantly higher than that in normal liver tissue and increased with increasing cancer malignancy." (PMID 37038185, 2023). "E6 stabilizes a major cell cycle regulator protein CDC-10 dependent transcript-2/Cdt2/DTL by recruiting a deubiquitinase, USP46, which was discovered to be essential for proliferation and survival of the cancer cells." (PMID 37707654, 2023).
cancer (continued). "DTL, a homolog of E3 ubiquitin ligase that belongs to the DCAF protein family, was reported to enhance the motility, proliferation, and invasion of cancer cells, and also significantly decrease total glucose consumption and lactate production." (PMID 37312153, 2023). "DTL interacts with PDCD4 and promotes the ubiquitin-proteasomal degradation of PDCD4, thus enhancing cancer progression." (PMID 35983977, 2022). "Reportedly, DTL overexpression decreased the protein level and accelerated the degradation rate of PDCD4 by ubiquitination and in cancer tissues was significantly upregulated than in normal tissues." (PMID 32596316, 2020). "Through the detection of the EMT marker, we found that depletion of DTL attenuates the expression levels of N-cadherin and increased the expression level of E-cadherin, indicating that DTL promotes the process of EMT to induce the migration and invasion ability of cancer cells." (PMID 35103094, 2022).
tumor (40 papers, 2013 to 2026). "The strong association between DTL upregulation and adverse clinical outcomes, coupled with its multifaceted regulatory roles in tumor biology, highlighting its therapeutic potential as a novel target in BC." (PMID 40391156, 2025). "Overexpression of DTL drives L-lactate accumulation to promote tumor progression, nominating DTL as a dual diagnostic and therapeutic target in BC." (PMID 40391156, 2025). "By analyzing the statistical data of Ki-67 staining in our LIHC cohort, it was discovered that the expression of DTL has a significant positive association with Ki-67, which indicated that overexpression of DTL promotes tumor proliferation." (PMID 37038185, 2023). "In this study, our data revealed that DTL was one of the hub genes and an excellent diagnostic biomarker in BCa; it was remarkably upregulated in BCa tumor tissues, which was associated with higher TNM stage and worse survival." (PMID 35103094, 2022). "Overexpression of DTL, which plays a crucial role in tumor cell proliferation, is associated with poor survival rates and in GC." (PMID 29912172, 2018). "Particularly noteworthy was the consistent and striking finding within the BRCA study: the expression levels of both CDK1 and DTL were markedly elevated in tumor samples compared to other conditions." (PMID 39567714, 2024). "In this study, based on integrated bioinformatics analysis and experimental verification, it showed that DTL was highly expressed in almost all tumors, and overexpression of DTL was relevant to tumor progression." (PMID 37038185, 2023). "DTL expression was also associated with immune cell infiltration, TMB, MSI and the mutation of MMRs in the tumor microenvironment." (PMID 37038185, 2023). "Exploration of the transcriptome in specimens from 5 GEO datasets and the HCC cohort from both TCGA and ICGC databases proved that DTL expression is significantly overexpressed in tumor tissues than non-tumor specimens." (PMID 35392073, 2022). "The results revealed that the mRNA levels of the DTL gene in tumor samples were significantly elevated in these 6 cohorts from the GEO and TCGA databases (all p < 0.01)." (PMID 35392073, 2022). "In conclusion, this study reveals that the DTL gene is an underlying prognostic biomarker for patients with HCC and is related with the infiltrating levels of immune cells in the tumor microenviroment." (PMID 35392073, 2022). "KEGG enrichment, GO analysis, and GSEA results demonstrated that the tumor cells of patients with the DTL-overexpression phenotype were highly active in the process of cell cycle, DNA replication, and cell division." (PMID 35392073, 2022). "Overexpression of DTL induced the migration and invasion of tumor cells in vitro and promoted intra-pulmonary metastasis in vivo." (PMID 34635635, 2021). "Until now, DTL was thought to be involved in the regulation of cell cycle and DNA replication to influence tumor progression." (PMID 34712733, 2021). "The validation of the two main pro-oncogenic factors, TFRC and DTL, in an independent tumor sample cohort verifies the developed analysis pipeline and confirms a signature comprising 65 genes of primarily miRNA-dependent transcripts distinguishing ATC." (PMID 34885022, 2021). "The results indicated that DTL overexpression promoted tumor growth and DTL knockdown inhibited tumor growth in terms of tumor weight and volumes." (PMID 31409387, 2019). "The results of this study indicated that circ‐SKA3 and circ‐DTL were essential in tumor cell proliferation, migration, and invasion through regulating the expression of the host genes." (PMID 30402980, 2018). "To search for the mechanisms by which DTL overexpression facilitated tumor development, we first identified the genes that are transcriptionally co-expresssed with DTL in LuADC using TCGA data." (PMID 28336923, 2017). "Overexpression of the DTL protein was detected in GC cell lines (4/7 cell lines; 57%) and primary GC tumor samples (42/100 cases; 42%)." (PMID 26472028, 2015).
tumor (continued). "Our findings elucidate the multifaceted role of DTL in BC progression through its regulation of L-lactate production, which in turn coordinates a complex interplay of biological processes that collectively drive tumor aggressiveness." (PMID 40391156, 2025). "The results showed that overexpression of DTL significantly increased tumor growth and weight." (PMID 38609375, 2024). "To confirm whether the expression of DTL is related to tumor immune invasion, we detected the percentage of CD3+ T cells infiltrating in these tumor samples and analyzed its correlation with the expression of DTL." (PMID 37038185, 2023). "Then, we further investigated the role of DTL in tumor growth in the xenograft mouse model." (PMID 35103094, 2022). "Furthermore, denticleless protein homolog (DTL) has been associated with response to DNA damage and the immunosuppressive tumor microenvironment." (PMID 36670957, 2022). "Our above findings showed that high levels of the DTL gene in cells would lead to rapid tumor progression; however, how the behavior of pro-proliferation characteristics of HCC cells affects the microenvironment is unknown." (PMID 35392073, 2022). "In addition, our studies unraveled the upregulation of major pro-oncogenic drivers in ATC such as the E3-ubiqutin ligases DTL promoting the decay of tumor suppressors such as PDCD4 and the transferrin receptor TFRC (CD71)." (PMID 34885022, 2021). "Although DTL overexpression promoted the invasion and migration of cells in vitro, we extended our research to explore whether DTL could induce tumor metastasis in vivo." (PMID 34635635, 2021). "This study supposed that upregulated circ‐SKA3 and circ‐DTL might promote tumor cell proliferation and survival, migration capacity, and invasion ability in MB cells." (PMID 30402980, 2018). "Moreover, USP46 protein could mediate the stability of CDT2 and promote the growth of HPV-positive tumors, suggesting the potential role of DTL in tumor progression." (PMID 40385396, 2025). "In addition, the specific mechanism of DTL overexpression in tumor progression and immunotherapy in this study are relatively simple, and further in vitro and in vivo studies are needed to confirm our hypothesis." (PMID 37038185, 2023). "Interestingly, the close association of the DTL gene and markers of Treg cells and T cell exhaustion, such as FOXP3, CCR8, STAT5B, PD-1, CTLA4, and LAG3, was found after adjusting the correlation values for tumor purity." (PMID 35392073, 2022). "Furthermore, some scholars have reported that USP46 protein could mediate the stability of DTL (CDT2) and promote the growth of HPV-positive tumors, suggesting the potential role of DTL in tumor growth." (PMID 35392073, 2022). "Among these, seven genes, namely, RRM2, KIF11, ANLN, CDC20, YWHAZ, DTL, and PCNA, exhibited significantly elevated expression in tumor samples (p ≤ 0.05)." (PMID 41487287, 2025). "Overexpression of DTL, for instance, can decrease PDCD4 expression levels, promote intracellular PDCD4 ubiquitination, accelerate tumor cell growth, and enhance invasive capabilities." (PMID 39367897, 2025). "Usually combined with the cullin ring E3 ubiquitin ligase (CRL) to form a complex (CRLCDT2), DTL (CDT2) mainly plays a pivotal role in genomic stability within tumor cells, which is important for tumor cells to duplicate." (PMID 35392073, 2022). "In conclusion, we constructed a five DEGs (CCNB2, CDK1, DTL, GMNN, and UBE2C)-based prognostic signature for ACC and first identified GMNN as a novel tumor biomarker for predicting the malignant progression, mitotane efficacy, and prognosis of ACC." (PMID 36539849, 2022).
tumor (continued). "Previous studies show that as the tumor progresses, the number of Treg cells, the crucial immunosuppressive cells, increases, while, in our study, Treg cells infiltrate more in the DTLhigh group, hinting that patients with DTL overexpression might show some degrees of immunosuppression." (PMID 35392073, 2022). "For tumor stage, significant differences among stage 1, stage 2, and stage 3 were shown in NDC80, CCNB1, KIF20A, DTL, and TOP2A of the key genes from Jia Liver data set (P < 0.05)." (PMID 34746301, 2021). "mRNA expression of the candidate genes MEIS1, LDOC1, AGTR1, BAK1, TYMS and DTL were analyzed in 3 cell lines (Hep2, KB and SCC 084), 1 primary HNSCC tumor and 3 normal head and neck tissue samples." (PMID 25186767, 2014). "DTL (CDT2), which is often coupled with the cullin ring E3 ubiquitin ligase (CRL) to create a complex (CRLCDT2), primarily plays a crucial role in genomic stability inside tumor cells, which is required for tumor cells to replicate." (PMID 38969729, 2024). "The DTL gene is overexpressed in tumor tissues compared with distant non-malignant liver tissues, and DTL overexpression in HCC would enhance the HCC cells in the activities of cell cycle and division." (PMID 35392073, 2022). "In addition, DTL activated JNK through RAC1 and upregulated FOXO1 to induce epithelial–mesenchymal transition, and the migration and invasion of tumor cells." (PMID 34635635, 2021). "In addition, many studies have reported that hsa-miR-30a-5p is a tumor suppressor in GC, and recent studies have shown that CCNA2, MYBL2, DTL, and STMN1 are regulated by hsa-miR-30a-5p." (PMID 29912172, 2018). "Furthermore, the GEPIA database also confirmed that the transcriptional levels of the DTL gene in tumor tissues (T, rosaceous) were higher than those in non-tumor tissues (orange)." (PMID 35392073, 2022). "However, whether DTL is involved in the regulation of tumor radiotherapy has not been reported." (PMID 38609375, 2024). "The overexpression phenotype of DTL was also confirmed in the ICGC-JP cohort, which contains transcriptional profiles of HCC tumor tissues and distant non-malignant samples." (PMID 35392073, 2022).
DTL also shares sentences with these, for which no sentence is quoted: ovarian carcinoma (6 papers); head and neck squamous cell carcinoma (4); pancreatic cancer (3); female infertility (2); Infertility (2); sarcoma (2); acute pancreatitis (1); Alzheimer disease (1); bladder urothelial carcinoma (1); cervical tumors (1); cholestasis (1); cognitive defects (1); colorectal adenoma (1); hereditary disease (1); infection (1); influenza (1); invasive breast carcinoma (1); liver cirrhosis (1); lymph node metastasis (1); lymphoid neoplasm (1); male infertility (1); multiple myeloma (1); nasopharyngeal carcinoma (1); neuroblastoma (1); nevus (1); non-small cell lung carcinoma (1); ovarian teratoma (1); pancreatitis (1); phospholipidosis (1); renal carcinoma (1).
A further 5 diseases each share a sentence with DTL in 1 paper.